RAD1 (RAD1 checkpoint DNA exonuclease)
Description:
Component of the 9-1-1 cell-cycle checkpoint response complex that plays a major role in DNA repair. The 9-1-1 complex is recruited to DNA lesion upon damage by the RAD17-replication factor C (RFC) clamp loader complex. Acts then as a sliding clamp platform on DNA for several proteins involved in long-patch base excision repair (LP-BER). The 9-1-1 complex stimulates DNA polymerase beta (POLB) activity by increasing its affinity for the 3'-OH end of the primer-template and stabilizes POLB to those sites where LP-BER proceeds; endonuclease FEN1 cleavage activity on substrates with double, nick, or gap flaps of distinct sequences and lengths; and DNA ligase I (LIG1) on long-patch base excision repair substrates. The 9-1-1 complex is necessary for the recruitment of RHNO1 to sites of double-stranded breaks (DSB) occurring during the S phase.
Synonyms: hRAD1; REC1
Tractability: Small molecule: a structure with a bound ligand is known. PROTAC: ubiquitination databases record sites on it; a small molecule that binds it is known.
Target class: Enzyme; Hydrolase
Gene: Protein-coding gene on chromosome 5 (34,900,072 to 34,918,989, reverse strand). Ensembl gene ENSG00000113456.
Subcellular location: Nucleus
Subcellular location (Human Protein Atlas): Nucleoplasm; Vesicles
Pathways (Reactome):
DNA Repair: HDR through Single Strand Annealing (SSA); Presynaptic phase of homologous DNA pairing and strand exchange; Processing of DNA double-strand break ends
Cell Cycle: Activation of ATR in response to replication stress; G2/M DNA damage checkpoint
Disease: Impaired BRCA2 binding to RAD51
Gene Ontology:
Molecular function: protein binding; damaged DNA binding
Biological process: cellular response to ionizing radiation; DNA damage checkpoint signaling; meiotic recombination checkpoint signaling; substantia nigra development; DNA damage response; DNA repair
Cellular component: checkpoint clamp complex; chromosome; nucleoplasm; nucleus
Genetic constraint (gnomAD): Loss-of-function variants: 16 observed, 22.57 expected, observed/expected ratio (o/e) 0.71, 90% interval 0.48 to 1.08. The upper end of that interval is the gene's LOEUF score, 1.08, which puts it in group 4 of 6, group 1 being the genes least tolerant of losing a copy. Missense variants: 287 observed, 295.24 expected, observed/expected ratio (o/e) 0.97, 90% interval 0.88 to 1.07. Synonymous variants: 97 observed, 106.52 expected, observed/expected ratio (o/e) 0.91, 90% interval 0.77 to 1.08.
Homologues: Orthologues: chimpanzee RAD1 (100% identical), macaque RAD1 (100% identical), pig RAD1 (98% identical), dog RAD1 (95% identical), rabbit RAD1 (95% identical), mouse Rad1 (90% identical), rat Rad1 (90% identical), guinea pig RAD1 (88% identical), tropical clawed frog rad1 (84% identical), zebrafish rad1 (75% identical), Drosophila melanogaster Rad1 (28% identical), Caenorhabditis elegans mrt-2 (27% identical).
Diseases named in the same sentence as RAD1 in open-access papers:
RAD1 is named in the same sentence as 36 diseases in open-access papers, as found by Europe PMC text mining. Sharing a sentence is not in itself a finding about the gene and the disease. The quoted sentences say what the papers report.
skin tumor (3 papers, 2010 to 2022). "Another study has reported that mouse RAD1 deletion enhances susceptibility for skin tumor development." (PMID 36408135, 2022). "Besides, mouse RAD1 deletion is reported to enhance sensitivity for skin tumor development probably by maintaining genomic integrity." (PMID 35392867, 2022).
cervical cancer (2 papers, 2016 to 2017). A primary or metastatic malignant neoplasm involving the cervix. "A research suggested that the mutation in pathways containing RAD1 may predispose to cervical cancer transition." (PMID 29312619, 2017).
Infertility (2 papers, 2022). "Depletion of RAD1 in spermatocytes results in reduction in tubule size, infertility, and loss of germ cells." (PMID 35133275, 2022). "To assess if Rad1 CKO mice were infertile, we bred control and Rad1 CKO mice with wild-type females." (PMID 35133274, 2022). "Here, we report that testis-specific disruption of RAD1 in mice resulted in impaired DSB repair, germ cell depletion, and infertility." (PMID 35133274, 2022).
colorectal cancer (1 paper, 2021). A primary or metastatic malignant neoplasm that affects the colon or rectum. "Bacopasaponin C may have potential as a drug candidate for the treatment of colorectal cancer as well as other cancers that show impaired activity or expression of ERCC4 (XPF), the human homologue of RAD1." (PMID 33668176, 2021).
congenital heart disease (1 paper, 2020). A heart disease that is present at birth. "Interestingly, among eight cases of RAD1 pathogenic variants, two had congenital heart disease." (PMID 32296131, 2020).
esophageal cancer (1 paper, 2015). A primary or metastatic malignant neoplasm involving the esophagus. "LOH and MSI frequencies were evaluated at chromosomal regions known to be frequently altered in sporadic esophageal cancer with particular attention to loci nearby genes involved in DNA double strand break (DSB) or in the oxidative damage repair pathways (i.e. BRCA1, BRCA2, RAD1 and MSRA)." (PMID 25611972, 2015).
hereditary ovarian cancer (1 paper, 2022). "A previous study has reported that RAD1 knockdown decreases cell viability and increases cell sensitivity to cisplatin, and they demonstrated that RAD1 acts as a BRCA-like tumor suppressor in hereditary ovarian cancer." (PMID 36408135, 2022).
ovarian carcinoma (1 paper, 2022). A malignant neoplasm originating from the surface ovarian epithelium. "In ovarian cancer, RAD1 acts as a tumor suppressor in a BRCA-like manner." (PMID 36281462, 2022).
sarcoma (1 paper, 2023). A usually aggressive malignant neoplasm of the soft tissue or bone. "21% sarcoma cases showed mostly missense mutations and losses of the tumor suppressor PTEN, and 17% were characterized predominantly by amplifications of the cell cycle checkpoint gene RAD1." (PMID 36779660, 2023).
viral disease (1 paper, 2017). "Additional powerful biomarkers were identified for Pacific (Trim21, IFI) and Atlantic (CD9, RAD1, SACS, XAF1) salmon whereby assays did not work across species; if re-designed, these biomarkers may also contribute to the universal separation of viral disease states across species." (PMID 28702195, 2017).
tumor (19 papers, 2010 to 2024). "Among these genes, CDC25C, NEIL3, H2AFX, NBN, XRCC5 and RAD1 were all validated to be upregulated in NSCLC tumor tissues." (PMID 36408135, 2022). "Rad1, a tumor suppressor gene, is a component of the Rad9-Rad1-Hus1 complex, which senses DNA damage and stimulates base excision repair." (PMID 33419231, 2021). "It would be interesting to examine Rad1 expression in human cancer tissues to find out the role of Rad1 in human tumor development." (PMID 20334655, 2010). "To determine whether Rad1 functions to maintain genomic stability and prevent tumor development, we generated Mrad1 mutant mice by gene targeting." (PMID 20334655, 2010). "RAD1 plays crucial roles in DNA repair and cell cycle checkpoint control; however, the role of RAD1 in cancer is not completely understood, and there may be differences in its effects in different tumor types." (PMID 36408135, 2022). "Immunohistochemistry and immunofluorescence analysis showed that CDC25C, H2AFX, NBN, XRCC5 and RAD1 had positive strong expression in NSCLC tumor tissues and negative weak staining in normal lung tissues and mainly distributed in nucleus and cytoplasm." (PMID 36408135, 2022).
cancer (13 papers, 2010 to 2023). A tumor composed of atypical neoplastic, often pleomorphic cells that invade other tissues. "The ability of B. monnieri extracts to induce an apoptosis-like effect in yeast deleted for RAD1 as well as apoptosis in some cancer cells lines suggested an impact on DNA integrity." (PMID 33668176, 2021). "Possibly, regarding this phenomenon, the same gene has opposite prognostic functions in different cancers; however, gene methylation was inversely correlated with expression in most cases, expect for RAD1, ATR, and ATM." (PMID 34869316, 2021). "Knock out mouse model studies of CHK1, MCM4, and RAD1 all show embryonic lethality in homozygous null mice and increased cancer incidence in heterozygotes, similarly to BRCA1/2, which makes them compelling and worthy of following up with functional studies." (PMID 28591191, 2017). "Firstly, we evaluated the mRNA expression of six DDR-related genes in NSCLC tissues in GEPIA, which demonstrated that CDC25C, NEIL3, H2AFX, NBN, XRCC5 and RAD1 were all significantly higher expressed in NSCLC cancer tissues compared to with normal lung tissues." (PMID 36408135, 2022).
infection (5 papers, 2017 to 2025). The state of being infected such as from the introduction of a foreign agent such as serum, vaccine, antigenic substance or organism. "Using a genome-wide association mapping approach, we identified a new role for the GRAS transcription factor RAD1 in supporting infection by an oomycete root pathogen." (PMID 29186498, 2017). "RAD1 expression levels increased 48 h post-inoculation (hpi) when the PpWS21 housekeeping gene expression started to accumulate in host tissues, during the biotrophic infection stage where P. palmivora colonized the cortex." (PMID 29186498, 2017). "Importantly, we demonstrate a role for RAD1 in both infections of fully developed root systems of composite plants and seedling root infections." (PMID 29186498, 2017). "We assessed RAD1 expression levels during a time course of infection with P. palmivora LILI-YKDEL, which constitutively expresses an endoplasmic reticulum-targeted YFP, allowing for in vivo imaging of infection structures." (PMID 29186498, 2017). "Furthermore, RAD1 expression induction coincided with peak expression levels of the RXLR effector gene REX3 and the occurrence of haustoria, both indicators for the biotrophic stage of infection." (PMID 29186498, 2017).
RAD1 also shares sentences with these, for which no sentence is quoted: Burkitt lymphoma (3 papers); mantle cell lymphoma (3); B cell lymphoma (2); cryptococcal infection (2); diffuse large B-cell lymphoma (2); lymphoma (2); autism (1); breast carcinoma (1); bronchopulmonary dysplasia (1); Cn (1); Cognitive impairment (1); encephalomalacia (1); Fanconi anemia (1); genetic disease (1); IgA nephropathy (1); membranous nephropathy (1); multiple sclerosis (1); neuroblastoma (1); neurodegenerative disease (1); Parkinson’s (1); prostate carcinoma (1); Telangiectasia (1); xeroderma pigmentosum (1).